IL1B (interleukin 1 beta)
Diseases named in the same sentence as IL1B in open-access papers (continued):
Sharing a sentence is not in itself a finding about the gene and the disease.
lung carcinoma (307 papers, 2008 to 2026). "Specifically, the A allele is known to regulate IL-1β expression, which leads to the overproduction of this pro-inflammatory cytokine in various conditions, including lung cancer." (PMID 40506975, 2025). "High levels of IL-1β have been linked to the promotion of lung cancer in preclinical models and associated with poor prognosis in patients with NSCLC." (PMID 40116353, 2025). "In conclusion, this is the first study to identify IL-1B as a target gene in lung cancer cells, elucidating its association with the ERK signaling pathway." (PMID 39911279, 2025). "With regard to lung cancer, certain genetic variants of the IL-1β gene (e.g., the G allele of rs1143633) are protective." (PMID 41267807, 2025). "IL-1β-511C > T (rs16944) has been proposed to modulate lung cancer risk, and its functional role has been broadly studied." (PMID 38103126, 2024). "Another case–control study noted that subgroup analysis of rs16944, rs1143634, and rs1143623 IL-1β SNPs greatly affected lung cancer risk, particularly for males, current smokers, and SCC subdivisions." (PMID 38103126, 2024). "Single nucleotide polymorphisms (SNPs) in several cytokines, such as IL1B, IL-1RN, and IL-10, exhibited significant correlations with fatigue levels in survivors of lung cancer." (PMID 39564104, 2024). "Previous studies have linked elevated levels of C-reactive protein, IL-6, IFN-γ, and IL-1β to an increased risk of lung cancer." (PMID 39015494, 2024). "We identified four inflammatory mediators - SCF, IL-1β, IL-18, and IP-10 - involved in genetic susceptibility to lung cancer overall and in specific histologic subtypes, as well as differences based on smoking status." (PMID 38957317, 2024). "Other factors closely linked with inflammation in lung cancer include IL-1β, IL-4, IL-8, IL-11, IL-12, monocyte chemotactic protein (MCP)-1, and TGF-β." (PMID 38539448, 2024). "For example, several investigations have identified IL-1β as a prognostic factor in lung cancer, with elevated levels of IL-1β in blood or tumor tissue associated with poor existence." (PMID 36874133, 2023). "The present result of IL1B SNP rs3136558 (T>C) agrees with the finding that variant-allele carriers of IL1B SNP were at increased lung cancer risk among Caucasus-Danes7." (PMID 37147350, 2023). "IL-2 and IL-1b demonstrated significant associations with lung cancer risk as well, with odds ratios of 2.16 (95% CI: 1.20–4.91, p = 0.009) and 1.88 (95% CI: 1.09–3.54, p = 0.030), respectively, for patients with levels above 17 pg/mL and 22 pg/mL." (PMID 37373957, 2023). "In this case–control study of Northeastern-Chinese, we explored the role of haplotype-tagging single nucleotide polymorphisms (htSNP) tagging 95% of common haplotypes across the IL1B gene on lung cancer risk." (PMID 37147350, 2023). "Present interaction study have added evidence that related to inflammation and immunity IL1B, which is independent or combined with other factors such as smoking, is involved in lung cancer risk." (PMID 37147350, 2023). "The molecular mechanism underlying carcinogenic IL1B inflammatory-induced lung cancer is still unclear completely." (PMID 37147350, 2023). "A Caucasian-Danish prospective study showed that variant allele carriers of IL1B SNP rs1143627 (− 31T>C) were at increased risk of lung cancer [Dominant model: IRR (incidence rate ratio) (95% CI) = 1.51 (1.08–2.12)]7." (PMID 37147350, 2023). "IL-1β can create an inflammatory microenvironment that favours tumour initiation and promotion, leading to an increased risk of lung cancer." (PMID 37033918, 2023). "When stratified by smoking-duration, IL1B SNP rs1143633 was specifically associated with lung cancer risk among long-term smokers (> 20 years)." (PMID 37147350, 2023). "Genotype distributions and lung cancer risk for the three IL1B htSNPs in co-dominant, dominant, recessive, over-dominant and log-additive models after adjustment smoking-duration were analyzed." (PMID 37147350, 2023).
lung carcinoma (continued). "IL-1β, a proinflammatory cytokine, is associated with tumor progression in lung cancer patients in multiple studies." (PMID 37259369, 2023). "There are only few studies involving IL1B SNPs and lung cancer risk, retrieving only one study of Caucasia-Danes7." (PMID 37147350, 2023). "Recently, the Canakinumab Anti-inflammatory Thrombosis Outcome Study (CANTOS) trial incidentally demonstrated that inhibiting IL-1β is associated with a significantly reduced incidence and mortality of lung cancer." (PMID 37511306, 2023). "A human mAb, canakinumab, targeting the proinflammatory cytokine IL-1β, significantly decreased the risk of lung cancer in the Canakinumab Anti-inflammatory Thrombosis Outcomes Study." (PMID 35471938, 2022). "To explore the role of NLRP3 inflammasome responses in lung cancer with Qi-yin deficiency, we first detected the serum levels of IL-1β and IL-18." (PMID 35292015, 2022). "Cytokine gene single nucleotide polymorphisms (SNPs) of interleukin (IL)-1β, IL-4, and IL-16 genes have been reported to be associated with the risk of cancers, including renal cell carcinoma, gastric carcinoma, and lung cancer." (PMID 36034203, 2022). "In particular, a number of studies have identified IL-1β as a prognostic factor in lung cancer, with high levels of IL-1β in either serum or tumor tissue linked to poor survival." (PMID 35086565, 2022). "Baseline IL-1β and IL-2 levels in peripheral blood were associated with the occurrence of irAEs in lung cancer patients." (PMID 36091125, 2022). "Another study showed that the absorption of vesicles of lung cancer cells by macrophages promotes the production of M2-like phenotype by tumor-associated macrophages, which in turn produces IL-1β, which is beneficial to the survival of tumor cells." (PMID 34497634, 2021). "In lung cancer, tumor-associated macrophages have been suggested as the principal cellular sources of IL-1β secretion, and macrophage depletion alleviated N-methyl-N-nitroso-urea-induced pulmonary cancer development." (PMID 33686176, 2021). "One of the main products of inflammasome activation is IL‐1β which has been implicated in promotion of lung cancers." (PMID 32027447, 2020). "Studies on tumor immunosurveillance have proposed a strong relationship between lung cancer risk factors and alterations in IL-1β levels." (PMID 31174565, 2019). "In lung cancer, IL-1β serum concentrations are significantly higher in lung cancer patients compared with controls and levels are associated with a worse prognosis." (PMID 26759080, 2016). "Further, elevated IL1β gene expression in normal lung tissue has been linked to increased risk of developing lung cancer in an epidemiologic study." (PMID 23762239, 2013). "IL-1β is a proinflammatory cytokine and genetic variation in IL1B has been associated with risk of lung cancer and multiple myeloma." (PMID 24194923, 2013). "Notably, the depletion of macrophages and CD8+ T cells reverted the regression of tumors and inhibited the infiltration and expansion of neutrophils in the TME of breast and lung cancer IL-1β-deficient animal models." (PMID 39858071, 2025). "However, the IL-1β-511 CT genotype was linked to a decreased susceptibility to all lung cancer subtypes (p < 0.01)." (PMID 38103126, 2024). "Notably, our analysis revealed novel causal links between SCF, IL-1β, IL-18, and IP-10 in overall lung cancer as well as specific histological subtypes, highlighting important etiological roles for these cytokines." (PMID 38957317, 2024). "In ever smokers, we found that interferon gamma-induced protein 10 (IP-10) (OR = 0.861, 95% CI: 0.781-0.950, P = 0.003) was inversely associated with lung cancer risk, while IL-1β (OR = 1.190, 95% CI: 1.023-1.384, P = 0.024) was positively associated with lung cancer risk." (PMID 38957317, 2024).
lung carcinoma (continued). "This MR study found preliminary evidence that genetically predicted levels of four inflammatory cytokines—SCF, IL-1β, IL-18, and IP-10—may causally influence lung cancer risk overall, in specific histologic subtypes, and stratified by smoking status." (PMID 38957317, 2024). "Stratified by smoking status, interferon gamma-induced protein 10 (IP-10) (OR = 0.861, 95% CI: 0.781–0.950, P = 0.003) was inversely associated while IL-1β (OR = 1.190, 95% CI: 1.023–1.384, P = 0.024) was positively associated with lung cancer risk in ever smokers." (PMID 38957317, 2024). "This MR study found preliminary evidence that genetically predicted levels of four inflammatory cytokines—SCF, IL-1β, IL-18, and IP-10—may causally influence lung cancer risk in an overall and subtype-specific manner, as well as stratified by smoking status." (PMID 38957317, 2024). "We found that both IL-1α and IL-1β were predictive of elevated risk for lung cancer risk." (PMID 39236155, 2024). "Additionally, mutations found in lung cancer cells are associated with the IL-1β axis, making it a potential target for therapy." (PMID 37511306, 2023). "In addition, the lung cancer risk was associated with higher levels of IL-1β and IFN-γ than the LOD value (HR [95% CI]: 1.61 [1.11–2.32], 1.85 [1.26–2.72], respectively)." (PMID 38067398, 2023). "From a classical case–control approach in whole study, our main finding is that variant G-allele of IL1B SNP rs1143633 (A>G) associated with lower risk of lung cancer under dominant model and that variant C-allele of IL1B SNP rs3136558 (T>C) was at increased risk of lung cancer." (PMID 37147350, 2023). "Notably, IL-1β release and inflammation are also considered the driving force in silica- and asbestos-induced lung cancer, but EGFR mutations appear to be less frequent in never-smokers occupationally exposed to such mineral particles." (PMID 37696458, 2023). "Given the association between chronic inflammatory states and lung cancer, and the role of IL-1β as an upstream activator of a wide range of inflammatory cytokines and tumorigenesis, CRP may serve as a potential predictive biomarker of response." (PMID 37511306, 2023). "Our findings, together with a recent study showing that air pollutants cause an influx of macrophages into the lung and release of IL-1β, demonstrate that macrophage-derived IL-1β in the lung is a pivotal cytokine in the development and progression of lung cancer." (PMID 37441079, 2023). "Furthermore, polymorphisms in the IL1B promoter have been linked to the risk of lung cancer development." (PMID 37976123, 2023). "In addition, high expression of IL-1β is associated with low survival rates in lung cancer patients." (PMID 38188678, 2023). "Furthermore, a study indicated that the anti-proliferative effect of ATRA is associated with selective stimulation of IL-1β, a cytokine that directly prevents growth of lung cancer cells." (PMID 37700002, 2023). "And we assessed gene–gene or gene–gene–environment interactions between genes of pathway of cytokines and inflammatory response and gene expression (transcription) pathway related to lung cancer risk, including the interaction between IL1B htSNPs, PPP1R13L and POLR1G risk SNPs and smoking-duration." (PMID 37147350, 2023). "This study, although primarily designed as a cardiovascular outcomes trial, provided evidence that IL-1β inhibition may potentially benefit individuals at high risk for lung cancer." (PMID 35471938, 2022). "In recent years, it has been reported that IL-1β gene polymorphisms may be related to various cancer types, including gastric carcinoma, hepatic carcinoma, and lung cancer." (PMID 36034203, 2022). "Interestingly, the CANTOS trial, which enrolled over 10,000 cancer-free patients, showed that those treated with canakinumab (IL-1β blocking agent) had reduced lung cancer incidence and cancer-associated mortality." (PMID 36439171, 2022).
lung carcinoma (continued). "Moreover, a large number of studies have shown that in lung cancer with Qi-yin deficiency, IL-1β and other inflammatory factors are all upregulated, which plays an important role in promoting the development of lung cancer." (PMID 35292015, 2022). "Therefore, in lung cancer with Qi-yin deficiency, IL-1β and other interleukin pro-inflammatory factors are expressed in large quantities, which are also the main products of NLRP3 inflammasomes." (PMID 35292015, 2022). "In this study, we found that BFXJY could inhibit the tumor growth in lung cancer with Qi-yin deficiency by reducing the production of IL-1β and IL-18 and inhibiting NLRP3 inflammasome activation, which might be associated with the inhibition of PKC signaling." (PMID 35292015, 2022). "We discovered that a subset of non-small cell lung cancer cells underwent a gradually progressing epithelial-to-mesenchymal (EMT) phenotype following a 21-day exposure to IL-1β, an abundant proinflammatory cytokine in the at-risk for lung cancer pulmonary and the lung tumor microenvironments." (PMID 31941995, 2020). "In addition, NSCLC cells underwent a gradually progressing epithelial-to-mesenchymal (EMT) phenotype following exposure to IL-1β, an abundant proinflammatory cytokine in at-risk for lung cancer pulmonary and lung tumor microenvironments." (PMID 33537234, 2020). "Indeed, several studies have confirmed that high levels of C-reactive protein, IL-6, IFN-γ, and IL-1β were positively associated with lung cancer risk." (PMID 32802852, 2020). "For instance, canakinumab, a human anti-IL-1β monoclonal antibody that was shown recently to be associated with a reduced incidence of lung cancer, could be used to neutralise IL-1β in the tumour microenvironment." (PMID 31588122, 2019). "Some authors have proposed that IL-1β levels are elevated in and associated with lung cancer." (PMID 26881918, 2016). "An additive effect of mutant alleles in IL1B T-31C (odds ratio = 0.55, 95 % confidence interval = (0.31, 0.97)) was also found to be associated with high intensity of pain, depressed mood and fatigue in lung cancer patients." (PMID 26269716, 2015). "Together, these data suggest that IL-1β blockade might be particularly effective in treating lung cancer in the presence of oncogenic driver mutations, potentially making canakinumab more effective when combined with EGFR TKIs rather than with chemotherapy or immunotherapy." (PMID 40940992, 2025). "Therefore, the overall findings could suggest the significance of IL-1β rs16944 and IL-6 rs1800795 as independent risk factors for the development of lung cancer." (PMID 38103126, 2024). "In the Canakinumab Anti-Inflammatory Thrombosis Outcomes Study (CANTOS) that reported on the use of IL-1β blockade with canakinumab to reduce the risk of cardiovascular events, a planned secondary analysis demonstrated reduced risk of de novo diagnoses of lung cancer risk." (PMID 39236155, 2024). "A number of studies in patients with lung cancer treated with radiation suggest that elevated IL-1B, IL-6, IL-8, TNF-a, and/or TGF-B1 may associate with radiation-induced pneumonitis and/or fibrosis; however, less evidence is available concerning injury to the heart." (PMID 37796395, 2023). "Enhanced IL-1β secretion by tumor-associated neutrophils has also been described as a mechanism mediating drug resistance in experimental models of lung cancer, raising the hope that the inhibition of IL-1β signaling could also diminish the occurrence of tumor resistance incidences." (PMID 33494181, 2021). "Furthermore, (a) the high DNA methylation status of IL promoters in lung cancer cells or tissues was associated with low mRNA levels; and (b) an inverse correlation between DNA methylation of IL-1β, IL-6 and IL-8 gene promoters and their corresponding mRNA levels was observed." (PMID 25590298, 2015).
lung carcinoma (continued). "Exposure of THP-1-CS stimulated migration and invasion of A549 lung cancer, and neutralization of IL-6 and IL-1β reduced these pro-migratory effects, confirming cytokine involvement." (PMID 42075013, 2026). "Lung carcinoma epithelial cells (A549) and normal bronchial epithelial cells (16HBE) were stimulated with IL-1β and treated with viable and heat-treated probiotics." (PMID 40806088, 2025). "Single-cell RNA-seq datasets from patients and pre-clinical mouse models revealed that myeloid cells have the highest expression of IL-1β in breast and lung cancer." (PMID 39858071, 2025). "ScRNA-seq of lung cancer BM samples revealed that IL-1B was predominantly expressed by macrophages, microglia, and neutrophils." (PMID 41436606, 2025). "Lung cancer particles (L-MPs) induce the release of a key pro-inflammatory cytokine, IL-1β, from M2-like macrophages, which promotes lung cancer development." (PMID 40034694, 2025). "Exploratory analysis of inhibition of IL1β by Canakinumab (CANTOS trial) has been shown to significantly reduce lung cancer incidence and mortality." (PMID 41440526, 2025). "The CANTOS trial incidentally showed that canakinumab reduced lung cancer incidence and mortality, highlighting the potential of IL-1β blockade in suppressing malignancy." (PMID 41007766, 2025). "IL-1β inhibitors, such as rilonacept and canakinumab, have shown promise in reducing lung cancer incidence and mortality, as well as in the treatment of autoinflammatory relapsing fever syndrome and Still’s disease." (PMID 40166075, 2025). "Further validation demonstrated a positive correlation between IL-1B expression in the ERK signaling pathway and lung cancer through real-time fluorescence quantitative enzyme-linked reaction with immunoblotting assays." (PMID 39911279, 2025). "Macrophages activated by lung cancer-derived microparticles secrete the proinflammatory cytokine IL-1β, which enhances lung cancer progression." (PMID 40443670, 2025). "Patients with TB pleurisy also had higher IL-1B in their serum and pleural fluid than patients with lung cancer." (PMID 40725488, 2025). "Although the CANOPY studies did not meet their primary endpoints (PFS/OS in CANOPY-1; MPR in CANOPY-N), there is a strong preclinical and clinical rationale for targeting IL-1β in lung cancer." (PMID 40116353, 2025). "To gain insights into the role of NSCLC TEVs in modulating immune cell gene expression and sensitivity to IL-1β, we isolated PBMCs from lung cancer patients and co-cultured them with H1975, PC9, and PC9/OR TEVs prior to mRNA isolation." (PMID 40725070, 2025). "In a post hoc analysis of the Phase III cardiovascular CANTOS trial, canakinumab, a monoclonal anti-IL-1β antibody, significantly reduced the incidence of lung cancer." (PMID 41145465, 2025). "Given the critical role of IL-1β in tumor growth and metastasis in lung cancer, IL-1β inhibitor is being evaluated as an anti-inflammatory therapy in lung cancer patients." (PMID 40394619, 2025). "In lung cancer, studies have shown upregulation of inflammasome components like IL-1β and IL-18 in the serum of lung cancer patients as compared with adjacent lung tissues." (PMID 41376623, 2025). "Tumor-derived exosomal TRIM59 reprograms macrophages toward a tumor-promoting phenotype by inducing the proteasomal degradation of ABHD5, thereby activating the NLRP3 and enhancing lung cancer progression through increased IL-1β secretion." (PMID 40443670, 2025). "In support of the implication of the PI3K/Akt pathway in IL-1β signaling, the inhibition of Akt phosphorylation in lung cancer cells suppresses the activity of this cytokine and blocks NF-κB translocation into the nucleus." (PMID 39858071, 2025). "Our study investigates if immune biomarkers in the TME affect outcomes in patients with non–small cell lung cancer (NSCLC) treated with the IL-1β inhibitor canakinumab plus an ICI-based therapy and describes canakinumab effects on the TMEs in these patients." (PMID 40116353, 2025).